FADS1 (fatty acid desaturase 1)
Diseases named in the same sentence as FADS1 in open-access papers (continued):
Sharing a sentence is not in itself a finding about the gene and the disease.
tumor (continued). "Conversely, the average tumor volume with FADS1 silencing decreased by approximately one third compared with control group." (PMID 32332698, 2020). "When FADS1 was overexpressed, the average xenograft tumor volume was increased about twofold compared with NC group." (PMID 32332698, 2020). "Similar to SCD, FADS1 expression was lower in the growing tumor area compared to the peritumoral area and in the necrotic core compared to the peritumoral area." (PMID 32392704, 2020). "The expression of FADS1, AKT, mTOR, and S6K1 in tumor tissues was also determined by western blot and IHC, which was basically in accordance with the results in vitro that FADS1 increase the phosphorylation level of AKT, mTOR, and S6K1." (PMID 32332698, 2020). "In the growing tumor area, FADS1, FADS2, SCD, and SCD5 expression positively correlated when using the B2M gene as reference." (PMID 32392704, 2020). "In contrast, only fibroblasts and myofibroblasts showed detectable FADS1 expression in normal tissues, suggesting that these cell populations may be responsible for local FADS1 production in the tumor microenvironment." (PMID 41153716, 2025). "And using mouse tumor cells in immunocompetent mice may further help to assess the microenvironmental and immunological changes during FADS1 inhibition." (PMID 40121894, 2025). "Taken together, these results demonstrated that reduced FADS1 function suppressed tumor formation in vivo, suggesting that FADS1 inhibiting might have a therapeutic potential for RCC." (PMID 40121894, 2025). "The stable knockdown of FADS1 also significantly inhibits tumor formation in vivo." (PMID 38586033, 2024). "Subsequently, we investigated whether gut microbes were indeed involved in tumor promotion of FADS1." (PMID 37041160, 2023). "Celecoxib treatment inhibited the tumor-promoting effect of FADS1 and AA." (PMID 37041160, 2023). "Elimination of gut microbes almost completely abolished the FADS1 effect on tumor growth." (PMID 37041160, 2023). "However, in non-small cell lung cancer (NSCLC), FADS1 was downregulated in tumor tissue and patients with lower FADS1 had shorter survival." (PMID 36046053, 2022). "Jiao reported that FADS1 overexpression was positively correlated with tumor grade in BLCA." (PMID 34706720, 2021). "Compared with Con group, FADS1 depletion markedly inhibited tumor cell growth." (PMID 32332698, 2020). "Results showed that FADS1 depletion repressed tumor growth and tumor weight of xenograft tumors." (PMID 32332698, 2020). "FADS1 overexpression could promote LSCC tumor growth and metastasis both in vitro and in vivo by activating AKT/mTOR signaling pathway." (PMID 32332698, 2020). "To investigate whether FADS1 inhibition affects tumor cell proliferation, we performed immunofluorescence staining of proliferation marker Ki-67 in 786-o and A498 cells treated with increasing concentrations of the FADS1 inhibitor for 96 h." (PMID 38586033, 2024). "Therefore, we speculated that FADS1-AA axis may be a unified chain that promotes tumor growth by altering the intestinal microecology." (PMID 37041160, 2023). "In addition, we downregulated the expression of PGE2 by celecoxib treatment in FADS1-OE xenograft mouse models and found celecoxib could inhibit the FADS1-driven tumor growth." (PMID 32332698, 2020). "Although current data support the differential and cell-type-specific expression of FADS1 in CRC-relevant tissues, further experimental validation is required to elucidate the exact mechanisms by which FADS1 influences tumor development and progression." (PMID 41153716, 2025). "A recent study demonstrated that the FADS1-AA axis promotes prostaglandin E2 (PGE2) production in CRC cells and reshapes the gut microbiota, thereby directly contributing to tumor development." (PMID 41153716, 2025).
tumor (continued). "Given the significant increase in ATF3 expression in response to FADS1 inhibition, we set out to further investigate the potential role of ATF3 in mediating the impact of FADS1 inhibition on tumor cell growth." (PMID 38586033, 2024). "In this study, we demonstrate that FADS1 knockdown or pharmacological inhibition suppresses cell proliferation, alters cell cycle in RCC cells, and reduces tumor formation in vivo." (PMID 38586033, 2024). "Moreover, FADS1 may also play an important role in modulating the tumor microenvironment." (PMID 36046053, 2022). "We also found that both FADS1 and FADS2 were significantly upregulated in the organoid rim region and corresponding cellular tumor regions in patient tumors." (PMID 34059134, 2021). "miRNAs modulate the expression of numerous metabolic factors and enzymes, such as SREBF2, AKT2, G6PD, CPS1, FADS1, and ETNK1, which alter tumor cell responses to chemotherapeutic treatments." (PMID 27861141, 2016). "Additionally, a coordinated regulation between FADS1 and FADS2 was noted in response to the tumor microenvironment." (PMID 40430008, 2025). "Summarily, FADS1-AA axis in CRC cells modulate the intestinal microecology of enriched gram-negative bacteria via creating a high AA microenvironment, which promotes the conversion of AA to PGE2 and eventually encourages tumor growth." (PMID 37041160, 2023). "Similar to AA, FADS1 showed a tumor-promoting role in the orthotopic model, but not in the subcutaneous model or in vitro." (PMID 37041160, 2023). "Therefore, the aim of this study was to analyze the mRNA expression of desaturase genes—SCD, SCD5, FADS1, FADS2, and FADS3—in GBM in three tumor zones: necrotic core, growing tumor area, and peritumoral area." (PMID 32392704, 2020). "Given that the FADS1 gene is significantly overexpressed in adipose tissue and that the transverse and sigmoid colon are key sites for CRC, we further explored its cell type-specific expression patterns using single-cell RNA sequencing data from human white adipose tissue and CRC tumor samples." (PMID 41153716, 2025). "Thus, the tumor-promoting effect of FADS1-AA axis was unified, and mediated by enriched gram-negative gut microbes in CRC." (PMID 37041160, 2023). "Deletion of gram-negative bacteria also eliminated the tumor-promoting effect of FADS1." (PMID 37041160, 2023). "In addition, the expression of FADS1 in the growing tumor area was distinctly, although not statistically significantly, lower than in the peritumoral area." (PMID 32392704, 2020).
cardiovascular disease (17 papers, 2009 to 2025). "Moreover, some of the genes (CPS1, MTHFR, and FADS1,2) that show associations with metabolites and are involved in neuropsychiatric diseases, and/or inborn errors of metabolism are also involved in cardiovascular diseases." (PMID 33177615, 2020). "Recently, two independent studies showed that dietary intake of long-chain polyunsaturated fatty acids (for example, C20:3 and C20:4) modulates the association between genetic variation in FADS1 and serum lipid levels, and thereby potentially also modifies the risk of cardiovascular disease." (PMID 23414815, 2013). "SNPs in the FADS1 and FADS2 group of genes have been known to be strongly linked to an increased risk of cardiovascular disease." (PMID 39070486, 2024). "FADS1 is involved in endogenous synthesis of unsaturated fatty acids that are known to modulate the metabolism of lipids and lipoproteins and therefore also to be involved in cardiovascular diseases." (PMID 29989339, 2018).
metabolic disorders (11 papers, 2018 to 2025). "In this study, we identified four key genes, including FADS1, FADS2, GLB1, and PNPLA3, associated with both metabolic disorders and inflammation in MAFLD through bioinformatics methods." (PMID 41007773, 2025). "Genetic variation in genes encoding fatty acid desaturases, such as fatty acid desaturase 1 (FADS1), fatty acid desaturase 2 (FADS2), and SCD1, influences lipid metabolism and susceptibility to metabolic disorders." (PMID 41002979, 2025). "Nonetheless, our results are supported by some observational studies in which a modulation by diet on the association of the FADS1 and FADS2 genes with metabolic disorders like MetS has been reported." (PMID 35773659, 2022). "Altogether, the FADS1-rs174550 could be a genetic marker to identify subjects who are most suitable to receive dietary PUFA supplementation, establishing also a personalized therapeutic strategy to improve mitochondrial function in metabolic diseases." (PMID 39218219, 2024).
neurological diseases (3 papers, 2023 to 2025). "The results from MELODI Presto also identified and prioritized metabolic and neurological diseases as potential intermediates between omega-3 fatty acids or FADS1/FADS2 genes and cognitive function, which provided direction for future mechanistic studies." (PMID 38316767, 2024).
mental illness (2 papers, 2013 to 2020). "HOMA-IR was associated with a FADS1/2 haplotype in a population with severe mental illness taking antipsychotics." (PMID 24455201, 2013).
adenocarcinoma (1 paper, 2015). A common cancer characterized by the presence of malignant glandular cells. "According to GSE29060 data, in HT-29 adenocarcinoma cells after a demethylation treatment 4 transcripts showed a minimally decreased expression (TIMP1, FADS1, CYP27B and SULT1A1), while PTGS2 was found to be upregulated." (PMID 26482433, 2015).
infection (1 paper, 2021). The state of being infected such as from the introduction of a foreign agent such as serum, vaccine, antigenic substance or organism. "In contrast, decreased Fads1 expression at 6 hr post infection correlated with a marked reduction of FADS1-mediated conversion of DGLA in AA, irrespective of IFNγ stimulation." (PMID 34951591, 2021). "Fads1 and Elovl5 transcript levels were transiently repressed at 6hr post infection with Mtb, while on the opposite those of Fads2 were increased from 6hr until 24hr." (PMID 34951591, 2021). "The inverse regulation of Fads1/Elovl5, compared to Fasn/Fads2, at 6hr post infection with Mtb was surprising since all genes are targets of the LXR and SREBP1 regulators of FA metabolism." (PMID 34951591, 2021).
FADS1 also shares sentences with these, for which no sentence is quoted: metastatic tumors (3 papers); allergic rhinitis (2); Alzheimer disease (2); cardiac failure (2); myocardial infarction (2); osteosarcoma (2); venous thromboembolism (2); abdominal aortic aneurysm (1); acute lung injury (1); alcoholism (1); angina (1); aortic valve stenosis (1); autism spectrum disorder (1); B-cell lymphoma (1); benign neoplasm of colon (1); Bicuspid aortic valve (1); Breast tumors (1); Brody disease (1); chronic kidney disease (1); cocaine addiction (1); colitis (1); colorectal adenoma (1); delirium (1); dementia (1); dyslipidaemia (1); epilepsy (1); esophageal cancer (1); febrile seizures (1); generalized epilepsy (1); hypertriglyceridemia (1).
A further 27 diseases each share a sentence with FADS1 in 1 paper.